USP15 (ubiquitin specific peptidase 15)
Diseases named in the same sentence as USP15 in open-access papers (continued):
Sharing a sentence is not in itself a finding about the gene and the disease.
cancer (continued). "To test whether these data are reflected in human cancer models, we next analyzed USP15 expression in the large panel of comprehensively characterized Cancer Cell Line Encyclopedia (CCLE)." (PMID 33378683, 2020). "We have established that USP15 regulates HR and cancer cells' response to PARP inhibitor." (PMID 30874560, 2019). "Here we found that USP15 affected HR and cancer cells response to PARP inhibitor." (PMID 30874560, 2019). "USP15 is amplified in several cancers, including ovarian cancer." (PMID 29593334, 2018). "Furthermore, the possible connection between USP15 and cancer progression came from the discovery that USP15 exerts its deubiquitinating activity to stabilize several proto-oncogene proteins, such as E3 ubiquitin ligase MDM2 and type I TGF-β receptor." (PMID 28245560, 2017). "Comprehensive approaches such as proteomics are urgently needed to identify the entire set of protein substrates that are recognized by USP15, which would help us to understand the mechanisms by which USP15-mediated deubiquitination affects cancer and other diseases." (PMID 28245560, 2017). "USP15 is a multifunctional DUB whose context dependent function is mediated by the presence of cell specific substrates involved in multiple biologic mechanisms including cancer relevant pathways." (PMID 29299163, 2017). "We identified that the expression change of MIR381 (p-value < 0.83) contributes to the expression changes of RNA-binding protein 5 (RBM5) (p-value < 0.008) and ubiquitin specific peptidase 15 (USP15) (p-value < 6☓10-4) via significant miRNA regulations (p-value < 10-16) in cancer cells." (PMID 26897165, 2016). "Hence, in-depth understanding of the role and mechanism underlying USP15 activity in HCC will be conducive to determining the processes involved in HCC occurrence and development, which are of great significance for the treatment of this type of cancer." (PMID 39794359, 2025). "However, in some tumors, there is evidence that USP15 has both pro-oncogenic and tumor suppressor roles, indicating that the role of USP15 in cancer is complex and sometimes contradictory, and highlighting it as an important and promising target in tumor treatment." (PMID 39794359, 2025). "These enzymes have been implicated in key cancer-associated processes such as extracellular matrix degradation (MMP14, plasmin), tumor invasion and metastasis (CATB), immune regulation and signaling (USP15), and cancer-related proteolytic processing (ACE2, METAP1/2)." (PMID 40890441, 2025). "To evaluate whether USP15 is meaningful in cancer, we first looked into public databases." (PMID 39164728, 2024). "Therefore, further research based on the current evidence will lead to a better understanding of the role of USP15 in cancer and other diseases and may identify USP15 as a potential target for future treatment strategies." (PMID 33946990, 2021). "Besides, better knowledge of USP15 regulation and the expression levels in different tumor tissues will provide a concrete understanding of its role in different pathological and physiological processes, especially in cancers." (PMID 33946990, 2021). "Interestingly, USP15 has a dual function in the regulation of cancer progression." (PMID 33771975, 2021).
cancer (continued). "Moreover, USP4 and its paralog USP15 play both promoting and suppressing roles in cancer." (PMID 33681193, 2021). "In the present study, our results showed that USP15 is upregulated in MM patients and has pro-proliferative and anti-apoptotic roles in MM cells and xenograft tumors in nude mice, which is similar to the role in promoting oncogenesis observed in other cancers others." (PMID 30459344, 2018). "Thus, the conflicting functions of these USP15 substrates in cancer biology raise a question concerning whether USP15 is more likely to act as an oncogene or as a tumor suppressor." (PMID 28245560, 2017). "In our study, we found that USP15 can interact with LGALS3 and activate the AKT/mTOR pathway by phosphorylating the AKT and mTOR proteins to exert cancer-promoting functions." (PMID 39794359, 2025). "According to recent literature, USP3, USP4, USP11, USP15, and USP26 positively regulated TGF-β signaling in various cancer types." (PMID 39048965, 2024). "Therefore, USP15 may regulate cancer progression by participating in the cell cycle." (PMID 35203682, 2022). "USP15, which stabilizes the type I TGF-β receptor and enhances the TGF-β pathway, is upregulated in various cancers." (PMID 32268558, 2020). "Therefore, we next investigated whether USP15 is dysregulated in other cancer cell lines." (PMID 30874560, 2019). "However, the detailed function of USP15 in cancer remains unclear." (PMID 30874560, 2019). "Since USP15 also stabilizes MDM2 in cancer cells, in which MDM2 serves as a major survival factor, ablation of USP15 appears to inhibit tumor growth by both promoting anti-tumor T cell responses and causing tumor cell apoptosis." (PMID 30054854, 2018). "Since we have shown that USP15 is essential for maintaining HBx stability and that USP15 augments HBx-mediated oncogenic signals, one inference from our work is that compromising USP15 might be a novel approach to abrogate cellular transformation and serve as a target for anti-cancer therapy." (PMID 28074857, 2017). "Additionally, our study provides novel insights into the role of USP15 in EMT, a critical process in cancer metastasis." (PMID 40762380, 2025). "USP15 is a member of the ubiquitination-specific protease (USP) family, which can regulate protein ubiquitination, thereby affecting their stability, and is dysregulated in many cancers, but its expression and regulatory mechanism in HCC are unclear." (PMID 39794359, 2025). "In addition, USP8, USP15, USP9X and USP18 are also being reported by a growing number of top research institutes for their vital immunomodulatory functions in cancer progression." (PMID 37658402, 2023). "Furthermore, ECSIT is an adapter protein known to activate the NF-κB signaling pathway, and USP15 is a deubiquitinating enzyme (DUB) responsible for ubiquitin chain cleavage on known substrates, ultimately leading to cancer cell survival." (PMID 35574218, 2022). "Therefore, examining the splicing regulation of the splicing factor SRSF1 by USP15 and USP4 in cancer progression was our particular interest." (PMID 35027535, 2022). "Finally, if small-molecule inhibitors of USP4, USP15, and/or USP11 are developed, it will be interesting to pursue their potential in cancer therapy." (PMID 26455393, 2015).
cancer (continued). "Furthermore, both CCLE database and Genomics of Drug Sensitivity in Cancer (GDSC) database showed that USP15 expression was negative correlated with the efficacy of multiple chemotherapeutic drugs." (PMID 39164728, 2024). "Besides OTUB1, other DUBs, such as USPs family (USP1, USP7, USP8, USP15, USP22), OTUs family (OTUD7B, OTUD6B, A20, and OTUB2) and other DUBs have been identified to regulate the progression of various cancers and applied for clinical cancer therapy." (PMID 35715413, 2022). "Therefore, both USP15 and USP4 may be considered important prognostic biomarkers in human cancers." (PMID 35027535, 2022). "Our findings demonstrate that individual proteases—USP15, plasmin, and CATB—serve as strong subtype-specific biomarkers capable of distinguishing cancer patients from non-cancer individuals with high accuracy." (PMID 40890441, 2025). "In low USP15 and USP4 upon depletion, SRSF1 is down-regulated with substantial retention of the C-terminal intron sequences recognized as an altered isoform SRSF1-3, which is degraded by NMD and thus do not show any effects on cancer cell phenotype." (PMID 35027535, 2022).
tumor (47 papers, 2013 to 2026). "Consistent with previous studies, the staining score of USP15 was significantly associated with tumor-node-metastasis (TNM) stage." (PMID 39164728, 2024). "Together, these data show that Usp15 regulates tumor cell proliferation in a cell-autonomous manner and loss of Usp15 increases a cell’s ability to form allograft tumors." (PMID 38902237, 2024). "In a publicly available dataset (LIHC, GEPIA2) of HCC patients, we found the level of USP15 expression reduced in tumor tissue and associated with high survival rate." (PMID 36900163, 2023). "Functional network analysis showed that USP15 is involved in tumor-associated pathways, DNA replication, and cell cycle signaling through TGFβRI." (PMID 36213818, 2022). "In the recent study, predominant expression of USP15 was found to be associated with a decrease in tumor cell apoptosis and antitumor T cell response, as evidenced by preventing ubiquitin-dependent degradation of MDM2 in melanoma and colorectal cancer cell lines." (PMID 28245560, 2017). "In a screen of a cohort of GBM for aberrantly expressed genes to infer underlying molecular alterations, we identified Ubiquitin Specific Peptidase 15 (USP15) (12q14.1) to be associated with genomic deletions, suggestive of a potential tumor suppressing function in GBM." (PMID 29299163, 2017). "USP15 expression in human NSCLC tumor tissues and matched adjacent normal tissues was assessed by immunohistochemical staining." (PMID 40762380, 2025). "In the context of HCC, some studies have shown that USP15 is highly expressed in tumor tissues, promoting HCC cell proliferation and inhibiting apoptosis." (PMID 39794359, 2025). "USP15 was significantly overexpressed in NSCLC tumor tissues compared to adjacent normal tissues, as confirmed by immunohistochemistry." (PMID 40762380, 2025). "Ubiquitin specific protease 15, which our USP15 probe can measure specifically, has been shown to regulate multiple oncogenic signaling pathways and modulate immune responses in the tumor microenvironment." (PMID 40890441, 2025). "Immunohistochemistry analysis of tumor tissue samples from mice in each group was also conducted to assess USP15 expression levels." (PMID 39794359, 2025). "Next, we conducted qRT-PCR and WB experiments, which demonstrated positive correlations between levels of USP15 and those of molecules related to tumor stemness (CD133, EPCAM, SOX2, ALDH1 and OCT4)." (PMID 39794359, 2025). "USP15 expression was significantly higher in tumor tissues than in matched normal tissues, although no stage‐dependent trend emerged in this cohort." (PMID 40762380, 2025). "Collectively, these data identify USP15 as a tumor‐enriched protein in NSCLC and support its potential as a prognostic marker." (PMID 40762380, 2025). "First, it is imperative to conduct in vivo studies to validate the impact of USP15 on tumor growth, metastasis, and chemoresistance." (PMID 40762380, 2025). "The USP15-TBX3 axis is reactivated during tumorigenesis, and Usp15 knockout prohibits BRAFV600E-driven tumor development in a Tbx3-dependent manner." (PMID 38750011, 2024). "To validate the tumor suppressive function of Usp15, we first injected KC mice individually with one library or one newly designed sgRNA." (PMID 38902237, 2024). "Western Blot analysis revealed Usp15 expression in Usp15 heterozygous tumor cells, albeit at a reduced level compared to control tumors, indicating Usp15 functions as a haploinsufficient tumor suppressor." (PMID 38902237, 2024). "Depending on the specific malignancy, USP15 has been reported to exert either tumor-promoting or tumor-inhibiting effects." (PMID 38656882, 2024). "Deleting Tbx3 or Usp15 leads to tumor redifferentiation, which parallels their overdifferentiation tendency during development, exemplified by disrupted thyroid folliculogenesis and elevated differentiation factors such as Tpo, Nis, Tg." (PMID 38750011, 2024).
tumor (continued). "Together, these data indicate that Usp15 functions as a strong haploinsufficient PDAC tumor suppressor potentially by regulating tumor suppressive cytokine signaling pathway." (PMID 38902237, 2024). "IncuCyte system for live-cell imaging and analysis was used to determine tumor cells proliferation activity, and knockdown of USP15 was consistently inhibited the cell proliferation in both SGC7901 and BGC823 cells." (PMID 39164728, 2024). "Collectively, these results demonstrated that Usp15 participates in BRAFV600E-induced tumor development by maintaining Tbx3 abundance under genetic background." (PMID 38750011, 2024). "As the integrity of mitochondria is important for maintaining the OXPHOS process as well as tumor cell viability, we analyzed the functional and structural integrity of mitochondria in GC cells after USP15 knockdown." (PMID 39164728, 2024). "This action highlights USP15's role as a tumor suppressor by preventing the overactivation of Wnt signaling and subsequent tumor formation." (PMID 39678489, 2024). "Tumor-related proteins turned out to be regulated by USP15 via indirect interactions mediated by other proteins." (PMID 36900163, 2023). "We also tested the level of some downstream proteins of USP15 in the tumor samples from the mouse model." (PMID 36900163, 2023). "Previous research has indicated that USP15 plays a role in tumor development, but its regulatory function as an oncogene or tumor-suppressing gene has never been demonstrated." (PMID 36900163, 2023). "In accordance with our findings for the publicly available dataset LIHC, USP15 expression tended to be reduced in the tumor tissues of our patient cohort." (PMID 36900163, 2023). "To investigate a role of USP15 as a possible tumor suppressor, we subcutaneously injected Huh7 cells into BALB/c nude mice." (PMID 36900163, 2023). "This would indicate that the tumor suppression role of USP15 only happened in the early phase of HCC, and in the end phase, the tumor suppression role disappeared." (PMID 36900163, 2023). "Patients with tumor tissue of moderate or strong staining were assigned to a second group, high expression of USP15 (n = 26)." (PMID 36900163, 2023). "Inhibiting USP15 improves the T cell activation in vitro as well as boosts T cell responses to tumor burden and bacterial infection in vivo." (PMID 37658402, 2023). "USP15 has been shown to induce angiogenesis and promote tumor invasion and is a key protein involved in tumorigenesis." (PMID 36213818, 2022). "To date, USP15 is an attractive DUB target because of its involvement in both tumor growth and immunity processes." (PMID 35884430, 2022). "We observed USP15 expression in adenocarcinoma tissues of lung clearly and the expression level of USP15 was variable but generally increased through tumor tissues (middle and bottom)." (PMID 35027535, 2022). "Although USP15 transcripts are readily expressed within many tumor types, their expression is remarkably higher in AML samples." (PMID 34465865, 2022). "USP4, the closest paralogue of USP15, also influences several tumorigenic properties and plays critical roles in different physiological and pathological processes including tumor initiation and progression." (PMID 35027535, 2022). "By immunohistochemical analysis, we found that USP15 was a high expressed in tumor tissue sections from 3 of these patients." (PMID 36213818, 2022). "Usp15 KO mice have higher levels of effector T-cells, that infiltrate tumors and promote resistance to transplanted tumor growth." (PMID 29593334, 2018).